ESRP1 (epithelial splicing regulatory protein 1)
Diseases named in the same sentence as ESRP1 in open-access papers (continued):
Sharing a sentence is not in itself a finding about the gene and the disease.
tumor (continued). "Patients treated with tamoxifen with high ESRP1 expression had a significantly shorter overall survival (using the BreastMark microarray platform), and ESRP1 knockdown significantly inhibited tumor growth in vivo in endocrine-resistant ER-positive breast cancer." (PMID 38110955, 2023). "In addition, the silencing of ESRP1/2 in MCF-7 mirrored the changes observed between tumor samples with high versus low expression of the two genes." (PMID 35887187, 2022). "Epithelial splicing regulatory protein 1 (ESRP1), also known as RNA-binding motif protein 35A (RBM35A), is a key component in the EMT process in malignant tumors, and it has been shown to be one of the splicing factors associated with EMT in tumor metastasis." (PMID 36483049, 2022). "In addition, the knockdown of TET3 essentially mimicked tumor hypoxia to effectuate the pro-EMT splicing switch of ESRP1 targets." (PMID 34362878, 2021). "Therefore, the upregulation of miR-1206 is a critical mechanism by which circ_0092367 mediates its tumor suppressor roles in regulating the expression of ESRP1 and other EMT-related genes in PC cells." (PMID 34828307, 2021). "The tumor-promoting effect of circ-NOLC1 was inhibited by knockdown of ESRP1, CDK1, or RhoA expression in circ-NOLC1-overexpressing cells, which might act by modulating RhoA and CDK1 expression." (PMID 33483472, 2021). "Interestingly, we have previously reported that ESRP1 expression is steeply declined by EMT-transcription factors under tumor hypoxia, which, in turn, skews the cellular spliceome to support EMT and invasion." (PMID 34362878, 2021). "Finally, TIMER was used to analyze the relationship between ESRP1 and tumor immune cell infiltration." (PMID 32964032, 2020). "ESRP1, as a member of an RNA-binding protein family, is an exquisitely epithelial cell-type-specific splicing factor that regulates splicing genes involved in tumor progression." (PMID 32964032, 2020). "However, there was a remarkable downregulation of the ESRP1 mRNA expression in subgroup analyses based on tumor stage and lymph node metastasis status." (PMID 32964032, 2020). "Furthermore, ESRP1 expression showed a linearly increasing trend in concurrence with the 6 pathologic tumor stages, suggesting that ESRP1 mRNA expression is potentially correlated with tumorigenesis." (PMID 33194621, 2020). "Notably, normoxic regions (negatively stained for CAIX) of the tumor tissue correspond to strong hMENA11a and ESRP1 expression and reduced pSMAD2/3 expression." (PMID 33089214, 2020). "pointed out that the discrepant findings of these previous studies may be suggestive of the plastic role of ESRP1 expression in tumor-specific tissues in view of the relation to FGF signaling pathways between in vitro and in vivo settings." (PMID 33194621, 2020). "In silico analyses suggest that ESRP1 could be an important driver in tumor progression and NE differentiation, since its amplification frequency increase from primary tumors to NEPC." (PMID 33224888, 2020). "Interestingly, when analyzing exclusively tumor data, ESRP1 expression was significantly increased when the FGFR2 locus was concomitantly deleted." (PMID 31881796, 2019). "Finally, in multiple breast cancerdatasets, high levels of ESRP1, ESRP1/HAS2, and ESRP1/ZEB1 correlate with poorprognosis, supporting the relevance of ZEB1/ESRP1 and ZEB1/HAS2 axes in tumorprogression." (PMID 31069317, 2018). "This ESRP1-CD44v-xCT-GSH axis enables CD44v-positive breast CSCs to exhibit the distant metastasis to the lungs despite of the exposure to excessive ROS generated by tumor-entrained neutrophils (TENs)." (PMID 30053872, 2018). "Moreover, the ratio of specific GPR137 isoforms is different in tumor versus normal intestinal tissue, and expression of a specific ESRP1-dependent GPR137 isoform predicts CRC patient survival." (PMID 28975893, 2017). "This indicates a possible tumor-suppressive role of ESRP1 in CRC." (PMID 28975893, 2017).
tumor (continued). "Furthermore, the ratio of specific GPR137 isoforms varied in tumor versus normal intestinal human samples, and expression of a specific ESRP1-dependent GPR137 isoform predicted CRC patient survival." (PMID 28975893, 2017). "Altogether, these findings strongly support an important role for ESRP1 in promoting tumor growth." (PMID 28052020, 2017). "Interestingly, in a human sample of our collection where we had ALK-rearranged NSCLC and adjacent normal lung, we detected lower staining of ESRP1 protein in tumor cells than in the adjacent normal epithelial cells." (PMID 27119231, 2016). "Multivariate analysis were adjusted for patients age, gender, stage, and microsatellite status, and demonstrated for low compared to mean and high ESRP1 expression in tumor a borderline significance with HR=0.56, 95% CI 0.31-1.01, P=0.055 and HR=0.62, 95% CI 0.36-1.09, P=0.098." (PMID 27650542, 2016). "Strikingly, the same interplay between H3K4me3 and H3K27me3 occurs for master genes involved in the EMT process, such as PDGFRα, which is essential for Twist1 to promote tumor metastasis via invadopodia, and the splicing regulator ESRP1, which is repressed by Snail1 to promote EMT." (PMID 24367927, 2013). "An alternative explanation for these phenotypes could be that a reduction of Esrp1 could transform pluripotent cells, a conceivable scenario especially if considering the previous implication of human ESRP1 as a tumor suppressor gene and in EMT." (PMID 24015231, 2013). "Thus, we hypothesized that high-ESRP1 EOC cells may inhibit the infiltrating CD3 + CD8 + T cells by secreting the immunosuppressive cytokine INHBE in tumor microenvironment, thereby inhibiting tumor immunity and promoting tumor cell colonization and growth." (PMID 32467669, 2020). "Thus, we speculated that ESRP1 could reflect the immune cell status of tumor patients and could be a predictive target for immunotherapy." (PMID 32964032, 2020). "Thus, ESRP1 might have the potential to inhibit tumor development by regulating the immunosuppressive microenvironment." (PMID 32964032, 2020). "Furthermore, the molecular mechanisms by which TGF-β regulates the tumor cell cycle still remains unclear, and ESRP1 is an important target molecule downstream of the TGF-β signaling pathway." (PMID 31362365, 2019). "This may be due to the ability of ESRP1 to promote tumor growth in vivo." (PMID 28052020, 2017). "Modulating the ESRP1/2–FGFR2-IIIc axis can affect TAM phenotype, potentially enhancing anti-tumor effects, particularly in breast cancer." (PMID 41584352, 2026). "Using Smart-seq2, investigators further identified ESRP1/2 as critical regulators of FGFR2 splicing during EMT, thereby providing mechanistic insight into how splicing contributes to tumor plasticity." (PMID 41584352, 2026). "Developing new treatment strategies, such as restoring ESRP1 expression to inhibit EMT and tumor cell invasion or reducing tumor proliferation and metastasis through specific targeting of ESRP1-regulated splicing variants, is possible." (PMID 40046628, 2025). "In conclusion, ESRP1 plays an important role in OSCC by regulating the alternative splicing of genes and affecting pathways such as EMT in tumor cells and the tumor microenvironment." (PMID 40046628, 2025). "In hepatocellular carcinoma, ESRP1 was identified to bind to the pre-mRNA of PTPN12, thereby fostering the generation of circPTPN12 to suppress tumor progression." (PMID 39550559, 2024). "Most importantly, the re-expression of ESRP1 and ESRP2 in the invasive T24 BC cells significantly decreased the presence of circulating tumor cells and the occurrence of the lung metastasis." (PMID 37090731, 2023). "Studies have revealed the clinical significance of ESRP1 and ESRP2 in tumor progression and metastasis." (PMID 35887187, 2022). "The analysis of ESRP1 and ESPR2 mRNA levels revealed their relationship with specific molecular and clinical features of tumor samples." (PMID 35887187, 2022).
tumor (continued). "The epithelial regulatory SF, ESRP1, is down-regulated during the EMT and plays a critical role in tumor progression." (PMID 35085775, 2022). "The analysis of ESRP1/2 in MCF-7 has given important insights and significant correlation with tumor-observed analysis." (PMID 35887187, 2022). "For instance, ESRP1 increases the formation of circUHRF1 by targeting flanking introns in OSCC, thus promoting tumour migration." (PMID 35876041, 2022). "In addition, the tumor-promoting effect of circ-NOLC1 was reduced after ESRP1, CDK1, or RhoA knockdown in circ-NOLC1-overexpressing cells, thus we hypothesized that circ-NOLC1 might function as an oncogene through binding and modulating ESRP1, CDK1, and RhoA levels." (PMID 33483472, 2021). "For the TCGA cohort, after stratifying the clinicopathological characteristics by gender, age, tumor size, pathological stage and AJCC stage, ESRP1 showed significance in age(<=60), male, and AJCC stage I+II." (PMID 33976726, 2021). "In our TMA analyses, 12,140 (68.4%) were interpretable for ESRP1 and 12,962 (73.0%) for ESRP2 (out of a total of 17,747 tumor samples)." (PMID 33339518, 2020). "The high ESRP1 expression group had higher advanced FIGO stage, higher tumor grade and higher proportion of residual tumor ≥ 1 cm than the low ESRP1 expression group." (PMID 32467669, 2020). "The tumours of these three groups were separately subjected to IHC staining and the expression levels of CD31 (angiogenesis-related indicators), Ki-67, ESRP1 and E-cadherin were observed." (PMID 32641707, 2020). "Survival analysis showed that the tumor samples in the ESRP1-high (z-score ≥ 1.96; n = 56) sample group had significantly worse BCR-free survival and RFS compared to those in the ESRP1-low (z-score < 1.96; n = 359) sample group (p < 0.05)." (PMID 33194621, 2020). "Given the expressional differences between normal and tumor samples for FGFR2 isoforms and ESRP1, we next crossed these data with several clinico-pathological features made available by the TCGA consortium." (PMID 31881796, 2019). "More than half (183/348—53%) of tumor samples presented FGFR2-IIIb and ESRP1 overexpression and FGFR2-IIIc under-expression in comparison to the median expression of normal stomach samples." (PMID 31881796, 2019). "Most RBPs (11 out of 16) act as oncogenes and only 5 (TIA1, TTP, QKI, ESRP1, CELF2, and QKI) present tumor suppressive abilities." (PMID 31440515, 2019). "The analysis confirmed the presence of both ESRP1 and RBFOX2 protein expression in all tumor cell compartments, especially the nucleus." (PMID 27911856, 2017). "Consistent with the involvement of ESRP1 and ESRP2 in the EMT, recent studies have revealed the roles and clinical significance of these factors in tumor progression and metastasis." (PMID 28991261, 2017). "Our data provide the first evidence that ESRP1 is required for CRC cell anchorage-independent growth in vitro and tumor growth in vivo." (PMID 28052020, 2017). "Immunohistochemistry analysis confirmed that ESRP1 and RBFOX2 protein were expressed in all tumor tissue areas, in agreement with literature data, but with different intensity and distribution." (PMID 27911856, 2017). "Epithelial splice patterns were compared between cell models with conditional ESRP1 expression and CRC tumor tissues." (PMID 27650542, 2016). "The identified strong correlation between expression of ESRP1 and ESRP2 support the concept of a general coregulation in colon, both in tumor and non-tumor tissue cells." (PMID 27650542, 2016). "Another intriguing finding was the limited ability of ESRP1 to induce i14e splicing in non-cancerous gallbladder epithelial cell line (L-2F7), which suggests other tumor-intrinsic factors are also involved in ERBB2 i14e splicing." (PMID 39948369, 2025). "Functionally, ESRP1 suppressed DGC proliferation and metastatic dissemination, with its expression levels positively correlating with patient survival, consistent with a tumor-suppressive role." (PMID 40528239, 2025).
tumor (continued). "ESRP1 is an epithelial cell-specific RNA-binding protein that regulates the alternative splicing of multiple genes involved in epithelial mesenchymal transition (EMT), which plays a critical role in metastasis by reducing tumor motility and invasiveness." (PMID 40528239, 2025). "Based on the PSI values of ESRP1 targets inferred by MRAS, tumor cells could be clearly distinguished from normal cells." (PMID 40323145, 2025). "The oncogene-enriched type mainly involves upregulated genes related to tumor cell proliferation and invasion, including Claudin3 (CLDN3), Claudin4, serine peptidase inhibitor Kazal type 1 (SPINK1), epithelial splicing regulatory protein 1 (ESRP1), and epithelial cell adhesion molecule (EpCAM)." (PMID 38611084, 2024). "However, there is also data indicating that high levels of ESRP1 and ESRP2 gene expression more generally contribute to aggressive prostate primary tumour development and correlate with poorer patient prognosis." (PMID 37752235, 2023). "Modulating expression of ESRP1 and ESRP2 in aggressive tumours could inhibit cell proliferation, but also have unintended side effects." (PMID 37752235, 2023). "Epithelial splicing regulatory protein 1 (ESRP1) is an RNA-binding protein and splicing factor specific to epithelial cells, which plays an important role in maintaining cell epithelial characteristics and regulating tumor progression." (PMID 38114495, 2023). "Here we discuss how expression of the splicing regulators ESRP1 and ESRP2, and how their role as “masterminds” of epithelial splicing patterns, have been identified as markers of aggressively proliferating prostate primary tumours." (PMID 37752235, 2023). "Could ESRP1 and ESRP2 also operate as lineage-survival oncogenes during the development of other tumours, many of which also develop from epithelial tissues?" (PMID 37752235, 2023). "Significantly smaller tumors were observed in mice grafted with either ESRP1 or ESRP2, compared to scrambled-grafted mice, while the reduction in tumor was even more pronounced in mice grafted with T24 cells transfected with combined ESRP1/2, shown by quantification, and by representative images." (PMID 37090731, 2023). "Coherently with the analysis of clinical data in relation to the ESRP1 and ESPR2 expression, most of the 27 ASEs were significantly related (p < 0.05) to the tumor molecular subtype (22 events), the fraction of altered genome (20 events), the menopause status, and the diagnosis age (8 events)." (PMID 35887187, 2022). "In contrast, ESRP1 is a marker of poor prognosis in ERα+ but not ERα− BC, and its depletion in ERα+ BC models reduces tumor growth." (PMID 35887187, 2022). "ESRP1 participates in AS of important transcripts, such as FGFR2, CD44, p120-Catenin (CTNND1), and hMena (ENAH) in regulating the process of EMT involved in tumor metastasis." (PMID 33495408, 2021). "Importantly, in the cell types analysed, ESRP1/2 and RBM47 induce the epithelial, basal A-like splicing phenotype, suggesting a potential tumour suppressor effect for these splicing regulators." (PMID 33845831, 2021). "We observed a significant negative correlation between ESRP1 levels and the Ki-67 proliferation index in these tumor samples (r = −0.521; p < 0.01)." (PMID 31362365, 2019). "Moreover, ESRP1 negatively correlated withboth ZEB1 and the extent of EMT across multiple datasets corresponding to invitro experiments and primary tumor samples." (PMID 31069317, 2018). "This suggests that even a low fold-change value in the ESRP1/RBFOX2 ratio correlates with a high risk of metastasis, regardless of tumor grade, receptor status or any other clinical feature." (PMID 27911856, 2017). "Our findings provide mechanistic insights into a previously unreported, pro-oncogenic role for ESRP1 in CRC, and suggest that fine-tuning the level of this RNA-binding protein could be relevant in modulating tumor growth in a subset of CRC patients." (PMID 28052020, 2017).
tumor (continued). "FGFR1 was not regulated in LS180 compared to SW480 cells indicating a tumor cell type dependent mechanism of IIIb/IIIc splice regulation by ESRP1." (PMID 27650542, 2016). "The CRC cell models with conditional ESRP1 expression demonstrated a similar splicing regulatory program in EMT as in CRC tumor and adjacent non-tumor cells." (PMID 27650542, 2016). "For example, tumor suppressor circ_0092367 could inhibit EMT and enhance GEM sensitivity in PC cells through regulating the miR-1206/epithelial splicing regulatory protein 1 (ESRP1) axis." (PMID 37560164, 2023). "Could ESRP1 and ESRP2 be lineage survival oncogenes in other kinds of tumour?" (PMID 37752235, 2023). "Hence re-expression of ESRP1 and ESRP2 proteins could in principle be part of a gene expression programme enabling successful metastatic growth once secondary tumours have seeded." (PMID 37752235, 2023). "Epithelial splicing regulatory protein (ESRP1) is an epithelial cell-specific RNA-binding protein that regulates the alternative splicing of multiple genes involved in epithelial–mesenchymal transition (EMT), which has a critical role in metastasis by reducing tumor motility and invasiveness." (PMID 36307405, 2022). "We first analyzed the differential expression of ESRP1 in the tumor and adjacent normal tissues from five patients by Western blot, which revealed that the expression of ESRP1 was significantly decreased in SCLC tumor tissues as compared with corresponding adjacent normal tissues." (PMID 33495408, 2021). "Tumor cells from KPC mice were highly heterogeneous, leading toestablishing distinct epithelial and mesenchymal cell lines from these cells.Consistent with experimental data, epithelial cells expressed high ESRP1 and lowZEB1, while mesenchymal cells expressed high ZEB1 and low ESRP1." (PMID 31069317, 2018). "Survival analysis showed that the tumor samples in the ESRP1-high group had significantly worse BCR-free survival and RFS compared to the ESRP1-low group (p < 0.05), whereas OS was not (p=0.08)." (PMID 33194621, 2020). "For example, we found that E-cadherin, ESRP1 staining was greatly increased in tumors from CDX2;APC;PID mice, whereas Msi1 was decreased in these tissues, relative to tumor tissue from animals lacking PID expression." (PMID 30150766, 2018). "Most of CRC cases studied (~70%) demonstrated reduced expression of both ESRP1 and ESRP2 in tumor cells compared to adjacent non-tumor tissue." (PMID 27650542, 2016). "A further evaluation of RAC1b-specific exon inclusion, using the percent spliced in (PSI) approach, showed that there is a significant and positive correlation between ESRP1 and PSI values for RAC1 in 452 tumor samples, but not in the corresponding 41 normal samples." (PMID 34439247, 2021).
breast (3 papers, 2018 to 2020). "Importantly, ISG15 promoted ISGylation of ESRP1 and slowed the degradation of ESRP1, which demonstrated that ESRP1 and ISG15 formed a positive feedback loop and jointly suppressed EMT of lung ADC." (PMID 32641707, 2020).